TGM1 (transglutaminase 1)
Description:
Catalyzes the cross-linking of proteins and the conjugation of polyamines to proteins. Responsible for cross-linking epidermal proteins during formation of the stratum corneum. Involved in cell proliferation.
Synonyms: TGK; KTG; TGASE; LI; LI1; ARCI1; ICR2
Tractability: Small molecule: a high-quality ligand is known; it belongs to a druggable protein family. Antibody: its Gene Ontology location is reachable by antibodies, with high confidence; the Human Protein Atlas places it where antibodies can reach. PROTAC: ubiquitination databases record sites on it; a small molecule that binds it is known.
Target class: Protein-glutamine glutamyl-transferase; Enzyme; Aminoacyltransferase
Gene: Protein-coding gene on chromosome 14 (24,249,114 to 24,264,432, reverse strand). Ensembl gene ENSG00000092295.
Subcellular location: Cell membrane; Cytoplasm, cytosol
Subcellular location (Human Protein Atlas): Plasma membrane; Vesicles
Pathways (Reactome):
Developmental Biology: Formation of the cornified envelope
Gene Ontology:
Molecular function: identical protein binding; protein binding; protein-glutamine gamma-glutamyltransferase activity
Biological process: cornification; keratinocyte differentiation; positive regulation of cell cycle; positive regulation of keratinocyte proliferation; cell envelope organization; peptide cross-linking; protein modification process; animal organ development
Cellular component: cytosol; extracellular exosome; membrane; plasma membrane; cornified envelope
Genetic constraint (gnomAD): Loss-of-function variants: 63 observed, 91.79 expected, observed/expected ratio (o/e) 0.69, 90% interval 0.56 to 0.85. The upper end of that interval is the gene's LOEUF score, 0.85, which puts it in group 3 of 6, group 1 being the genes least tolerant of losing a copy. Missense variants: 996 observed, 1,160.4 expected, observed/expected ratio (o/e) 0.86, 90% interval 0.81 to 0.9. Synonymous variants: 415 observed, 448.87 expected, observed/expected ratio (o/e) 0.92, 90% interval 0.85 to 1.
Homologues: Orthologues: chimpanzee TGM1 (99% identical), macaque TGM1 (98% identical), dog TGM1 (92% identical), pig TGM1 (91% identical), rat Tgm1 (91% identical), guinea pig TGM1 (90% identical), mouse Tgm1 (90% identical), rabbit TGM1 (90% identical), tropical clawed frog tgm1 (51% identical), zebrafish tgm1l1 (47% identical), zebrafish tgm1 (45% identical), zebrafish tgm1l4 (41% identical), and 3 more. Paralogues in human: F13A1 (37% identical), TGM6 (32% identical), TGM7 (31% identical), TGM4 (31% identical), TGM2 (30% identical), TGM5 (30% identical), TGM3 (29% identical), EPB42 (22% identical).
Diseases named in the same sentence as TGM1 in open-access papers:
TGM1 is named in the same sentence as 84 diseases in open-access papers, as found by Europe PMC text mining. Sharing a sentence is not in itself a finding about the gene and the disease. The quoted sentences say what the papers report.
ichthyosis (38 papers, 2008 to 2025). Disorders of cornification that are characterized by visible scaling and/or hyperkeratosis of most or all of the skin. "In this study, we analyzed the functionality and safety of an adeno-associated viral vector of serotype 2 encoding TGM1 (AAV2-TGM1) for gene therapy of lamellar ichthyosis." (PMID 41155269, 2025). "In a cohort of kindreds with ichthyosis, several clinical characteristics associated with TGM1 variants were identified." (PMID 39408635, 2024). "Missense variants in TGM1 have been identified in few ichthyosis patients with clinical phenotypes of self-improving collodion ichthyosis and truncated variants have caused severe forms of LI pictures." (PMID 36676727, 2023). "The chances of collodion membrane, ectropion, and alopecia are four times more expected in ARCI patients with mutations in the TGM1 gene compared to those who have mutations in other known genes causing ichthyosis." (PMID 36676727, 2023). "Ichthyosis vulgaris results from an autosomal dominant mutation in the filaggrin gene, and lamellar ichthyosis results from mutations in transglutaminase-1, the major cross-linking enzyme in the stratum corneum." (PMID 38203406, 2023). "In this work, the ocular clinical characteristics in a series of Mexican patients with lamellar ichthyosis due to TGM1 mutations are described." (PMID 37542530, 2023). "In three patients with non-syndromic ichthyosis (M1, B1 and Y1), the involved gene was TGM1 with two different homozygous nonsense germline mutations." (PMID 34983512, 2022). "A loss of function variant in the TGM1 gene encoding transglutaminase 1 leads to autosomal recessive ichthyosis in Jack Russell terriers due to calcium dependent cross-linking of peptides (e.g. involucrin, loricrin) involved in forming the cornified envelope." (PMID 36251712, 2022). "A vector based on herpes simplex virus type 1 (HSV-1) encoding the TGM1 gene has been proposed as a safe and effective method for gene therapy of ichthyosis caused by the TGM1 gene mutation." (PMID 35269649, 2022). "Tgm1 defects have been associated with aberrant cornification and ichthyosis, whereas Tgm2 acts in many tissues and stabilizes extracellular matrices." (PMID 34956208, 2021). "An unusually high frequency of the lamellar ichthyosis TGM1 mutation, c.1187G > A, has been observed in the Ecuadorian province of Manabí." (PMID 31073126, 2019). "Bathing suit ichthyosis (BSI) is a rare variant of autosomal recessive congenital ichthyosis (ARCI) due to transglutaminase-1 gene (TGM1) mutations leading to a temperature sensitive phenotype." (PMID 30693114, 2018). "In contrast, calprotectin was intensely positive in the epidermis of lesional ichthyosis skins with those TGM1 mutations, as well as in lesional epidermis of psoriasis." (PMID 27442430, 2016). "Mutations in the TGM1 gene encoding transglutaminase 1 are a major cause of autosomal recessive congenital ichthyosis." (PMID 22511925, 2012). "TGM1 mutations in humans result in lamellar ichthyosis characterized by scaly and thick skin." (PMID 39408635, 2024). "In Jack Russell Terriers, related the lamellar ichthyosis to a LINE-1 insertion in the transglutaminase 1 (TGM1) gene, which encodes an enzyme with a role in cornified envelope formation, and 30–40% of humans with non-epidermolytic (lamellar) ichthyosis present mutations in this gene." (PMID 36006348, 2022). "Further studies are required to clarify whether the changed expressions of many ARCI genes in patients with TGM1 mutations are unique for this type of ichthyosis or represents ingredients of a general barrier repair mechanism." (PMID 30372788, 2019).
ichthyosis (continued). "However, patient P4 (age 80, homozygous for a splice site mutation in TGM1 and acitretin‐treated for 20 years) showed more equivocal results despite overt lamellar ichthyosis." (PMID 30372788, 2019). "Interestingly, this condition is also maintained in the lesional skin of a BSI patient with the TGM1 mutation and possibly contributes to hyperplasia of the epidermis in the ichthyosis." (PMID 27442430, 2016). "Mutations in transglutaminase-1 (TGM1) gene lead to the development of LI and rarer ARCI form bathing suit ichthyosis (OMIM #242300)." (PMID 35269649, 2022). "Tgm1−/− mice have similar skin features to severe forms of ichthyosis but die within the first hours of life due to impaired skin barrier function." (PMID 35269649, 2022). "Defects in keratinocyte TGM1, resulting in an improper protein scaffold for deposition of the lipid barrier, comprise a major source of autosomal recessive congenital ichthyosis." (PMID 36423088, 2022). "Several topical gene therapies using modified herpes simplex virus (HSV) carrying wild‐type genes such as COL7A1 for RDEB or transglutaminase 1 (TGM1) for autosomal recessive congenital ichthyosis have been developed." (PMID 33657662, 2021). "Taken together, the present study of four Pakistani families supports previous research that biallelic mutations in TGM1, SULT2B1, SPINK5, and FLG cause human ichthyoses." (PMID 33807935, 2021). "TGase1 deficiency from a mutation in TGM1 (transglutaminase 1) encoding the TGase1 enzyme can cause lamellar ichthyosis, an autosomal recessive congenital ichthyosis." (PMID 32054030, 2020). "Since the genetic basis for most types of ichthyosis has been elucidated, this information is now increasingly used for differential diagnosis and nomenclature, e.g., LI(TGM1) for lamellar ichthyosis (LI) due to transglutaminase-1 deficiency." (PMID 24130705, 2013). "Humans with lamellar ichthyosis have severe hair abnormalities and skingrafted from murine TGM1−/− neonates develop abnormal hair follicles." (PMID 22496784, 2012). "To date, multiple genes have been shown to be associated with ichthyosis, including ALOXE3, ALOX12B, TGM1, CYP4F22, NIPAL4, and ABCA12." (PMID 24278723, 2012). "Mutation of the TGM-1 gene leads to a lack of TGM-1 enzyme, which results in a type of congenital ichthyosis known as mellar ichthyosis." (PMID 34445570, 2021). "Patient SA‐13, diagnosed with SII based on the lack of signs for congenital ichthyosis aside from the presence of a collodion membrane at birth, presented a homozygous missense variant in exon 5 of TGM1, c.871G>A (p.Gly291Ser)." (PMID 30600594, 2019). "In lamellar ichthyosis-affected Jack Russell Terriers only a small amount of transglutaminase 1 (TGM1) protein could be detected on immunoblotting triggered by an insertion that disrupted the expression of TGM1." (PMID 26506231, 2015). "In such case, ichthyosis and hypothyroidism could be co-inherited, since the TGM1 and TSHR genes maps to the same chromosome localization (14q)." (PMID 23192619, 2013). "There are 6 genes currently known to be associated with ichthyosis: ALOXE3, ALOX12B, TGM1, CYP4F22, NIPAL4, and ABCA12, and although thought to be unrelated, both the probands from family 1 and family 2 harboured an identical novel missense variant, c.G4676T, p.Gly1559Val in ABCA12." (PMID 24278723, 2012). "Interestingly, the same loss-of-function mutation in TGM1 and TGM5 have been shown to cause lamellar ichthyosis, a disease characterized by excessive scaling and shedding of the outer epidermis, and peeling skin syndrome, respectively." (PMID 19107207, 2008). "Other dog models for human non-syndromic ichthyoses include Norfolk Terriers with an epidermolytic ichthyosis caused by a KRT10 variant, Bulldogs with ARCI caused by a NIPAL4 variant, and Jack Russell Terriers with another form of ARCI caused by a TGM1 variant." (PMID 28249031, 2017).
ichthyosis (continued). "Coexistence of TGM1 and FLG mutations in a newborn with congenital ichthyosis is not well described in the literature." (PMID 37736478, 2023). "Most well documented forms of canine ichthyosis are non-epidermolytic, involving genetic variants in ABHD5 or PNPLA1 in golden retrievers, TGM1 in Jack Russell terriers, NIPAL4 in American bulldogs, and ASPRV1 in a German shepherd dog." (PMID 36251712, 2022). "Ten patients suffered from congenital ichthyosis, seven of them having lamellar ichthyosis (Ichthyn: n 4, CYP4F22: n 1, TGM1: n 1, ongoing analysis: n 1) and three cases of congenital ichthyosiform erythroderma (two patients who carried ABCA12 mutations, and one who had no identified mutation)." (PMID 29618363, 2018).
autosomal recessive congenital ichthyosis (18 papers, 2012 to 2025). Autosomal recessive form of inherited ichthyosis. "Mutations in TGM1 are linked to autosomal recessive congenital ichthyosis (ARCI), a hereditary disorder of cornification, which is mainly characterized by the presence of collodion membrane, alopecia, as well as dry, thickened, and scaly skin." (PMID 39092175, 2024). "Mutations in genes such as transglutaminase-1 (TGM1), which are responsible for the formation and normal functioning of a lipid barrier, lead to the development of autosomal recessive congenital ichthyosis (ARCI)." (PMID 35269649, 2022). "Since inactivating mutations of TGM1 are the predominant cause of the skin disease autosomal recessive congenital ichthyosis, this class of protein tyrosine phosphatase inhibitor would be inadvisable for therapeutic use in epidermis." (PMID 32864202, 2020). "Structure-function implication on a novel homozygous Trp250/Gly mutation of transglutaminase-1 (TGM1) observed in a patient of autosomal recessive congenital ichthyosis is invoked from a bioinformatics analysis." (PMID 25180191, 2014). "Additionally, tofacitinib, a broad-spectrum Janus kinase (JAK) inhibitor, has been suggested as a potential treatment for TGM1-associated autosomal recessive congenital ichthyosis (ARCI), characterized by elevated transepidermal water loss." (PMID 39408635, 2024). "Mutations in TGM1 were thought to be associated with “autosomal recessive congenital ichthyosis (ARCI),” which was characterized by hyperkeratotic, dry, thickened, scaling skin." (PMID 39092175, 2024). "Several local gene therapies have been developed using modified herpes simplex virus 1 (HSV-1) vector carrying wild-type genes, such as COL7A1 for recessive dystrophic epidermolysis bullosa or TGM1 for autosomal recessive congenital ichthyosis." (PMID 41155269, 2025). "Autosomal recessive congenital ichthyosis (ARCI) is associated with mutations in at least 10 genes, such as TGM1, ALOXE3, ALOX12B, ABCA12, and others." (PMID 40565081, 2025). "Based on clinical examination and genetic testing, a diagnosis of SICB was confirmed, with mutations identified in genes commonly associated with autosomal recessive congenital ichthyosis, such as ALOX12B, TGM1, ALOXE3, CYP4F22, and PNPLA1." (PMID 40193669, 2025). "Eight patients were affected by autosomal recessive congenital ichthyosis associated with ALOX12B, NIPAL4, and TGM1 mutations." (PMID 38791074, 2024).
lamellar ichthyosis (15 papers, 2012 to 2025). A keratinization disorder characterized by the presence of large scales all over the body without significant erythroderma. "Lamellar ichthyosis is caused by mutations in the TGM1 gene encoding transglutaminase 1 (TGM1), leading to a functional deficiency of the enzyme in the epidermis." (PMID 41155269, 2025). "The TGM1 gene is most frequently mutated in patients with lamellar ichthyosis (LI); so far, 242 different genetic variants have been identified in TGM1." (PMID 36676727, 2023). "Of these, TGM1 (transglutaminase 1) is thought to be one of the major causes for lamellar ichthyosis." (PMID 24995134, 2014). "Mutations of TGM1 (keratinocyte transglutaminase 1), a calcium dependent enzyme that functions in cross-linking of epidermal structural proteins and lipids into the CE, cause lamellar ichthyosis." (PMID 23226340, 2012). "A lack of TGM1, and thus a defective cross-linked protein envelope, is a major cause of the human scaly skin disease lamellar ichthyosis, and mice with the gene ablated are not viable after birth." (PMID 35294467, 2022). "The identified variant results in premature termination of transcribed mRNA and is predicted to cause a truncated or absent translation product transglutaminase-1 (TGase-1) accompanied by loss of catalytic activity, causing a severe clinical phenotype of lamellar ichthyosis in the patients." (PMID 36676727, 2023).
congenital ichthyosis (12 papers, 2012 to 2025). "Additional samples were collected from the forearms of subjects with ichthyosis vulgaris (filaggrin (FLG) deficiency), recessive X-linked ichthyosis (steroid sulfatase (STS) deficiency) and autosomal recessive congenital ichthyosis type lamellar ichthyosis (transglutaminase 1 (TGM1) deficiency)." (PMID 24130705, 2013).
psoriasis (10 papers, 2011 to 2025). An autoimmune condition characterized by red, well-delineated plaques with silvery scales that are usually on the extensor surfaces and scalp. "Previous studies have demonstrated the role of TGM1 as a biomarker for psoriasis and the involvement of TGM5 in the pathogenesis of peeling skin syndrome." (PMID 41380997, 2025). "PLA2G4D, TGM1, and IL36RN are all described to be involved in the psoriasis." (PMID 27774448, 2016).
gastric cancer (6 papers, 2020 to 2024). A primary or metastatic malignant neoplasm involving the stomach. "Research has shown that the loss of TGM1 inhibits gastric cancer cell proliferation in human cancer cells, where it increases apoptosis by arresting cells in the G0/G1 phase and altering the expression levels of Bcl-2 and Bax." (PMID 39408635, 2024). "There is also evidence suggesting that TG1 may regulate gastric cancer through the Wnt/β-catenin signaling pathway, as the loss of TGM1 significantly inhibits Wnt/β-catenin signaling, which is linked to enhanced cell proliferation and decreased cell death." (PMID 39408635, 2024). "In vitro experiments have also demonstrated a relationship between TGM1 and cell proliferation in gastric cancer cells." (PMID 38472489, 2024). "In gastric carcinoma TGM1 has been shown to promote the stem cell character and chemoresistance of tumor cells via modulation of the Wnt/beta‐catenin signaling pathway." (PMID 34060699, 2021). "In vitro experiments indicated the biological effect of TGM1 on gastric cancer cell proliferation and apoptosis." (PMID 32076707, 2020). "In addition, researchers found that the mechanism by which TGM1 regulates the development of gastric cancer may be related to the Wnt signaling pathway." (PMID 32546690, 2020). "In contrast, other transglutaminases including TGM1, TGM4, TGM5, TGM6, and TGM7 exhibited a significant decrease in gene expression in the gastric cancer tissue samples." (PMID 32467608, 2020).
melanoma (6 papers, 2020 to 2025). A malignant, usually aggressive tumor composed of atypical, neoplastic melanocytes. "Given that FLG, PKP1, and TGM1 are ECM related, their association with CTNND1 raises the possibility that altered adhesion dynamics converge with ECM remodeling to promote melanoma progression." (PMID 41321310, 2025). "Overall, this systematic meta-analysis of gene profiling was a step forward in the investigation of the mechanisms underlying melanoma's metastasis, and the role of SPRR1B, SPRR2B, TGM1, CDSN, and IVL in keratinocyte differentiation GO term needs to be further studied." (PMID 35003328, 2021). "The enrichment of these categories reflects the dysregulation of transcriptional programs typical of keratinocytes (e.g., SPRR1/2/3, KRT10/KRT16, LOR, IVL, EVPL, SCEL, TGM1/TGM3, CERS3, ACER1, DSP) and, above all, the epithelial crosstalk that influences melanoma biology." (PMID 41465101, 2025). "But the report of SPRR1B, SPRR2B, TGM1, CDSN, and IVL in melanoma was a gap." (PMID 35003328, 2021).
alopecia (4 papers, 2020 to 2024). Hair loss usually from the scalp. "The enrolled patients presented alopecia which has been reported in other patients with TGM1 mutations." (PMID 36676727, 2023). "Ears deformity was reported in two patients (B1 andY1) and alopecia in one patient (M1) carrying TGM1 mutation." (PMID 34983512, 2022). "Alopecia was found to be significantly associated with TGM1 mutations." (PMID 34983512, 2022).
acral peeling skin syndrome (3 papers, 2017 to 2020). Acral peeling skin syndrome (PSS) is a form of PSS characterized by superficial peeling of the skin predominantly affecting the dorsa of the hands and feet. "TGM1 deficiency impairs CE formation (ARCI1), TGM5 deficiency causes premature desquamation (peeling skin syndrome 2 (OMIM # 609796)), and TGM3 deficiency impairs hair shaft formation (uncombable hair syndrome 2 (OMIM # 617251))." (PMID 32218335, 2020).
Hyperkeratosis (3 papers, 2014 to 2021). Hyperkeratosis is a histopathological term defining a thickened stratum corneum and may be present in many different skin conditions, with many possible overlaps. "IL-1α is increased in ARCI and has been postulated to be a key cytokine involved in the hyperkeratosis in TGM1 deficiency using a rat organotypic culture model and rat Tgm1 siRNA." (PMID 27442430, 2016).